CHI3L1 (chitinase 3 like 1)
Diseases named in the same sentence as CHI3L1 in open-access papers (continued):
Sharing a sentence is not in itself a finding about the gene and the disease.
tumor (continued). "Among seven tumor-promoting inflammatory molecules significantly reduced in plasma and prostate tissue, CHI3L1 was identified as a key mediator." (PMID 40643503, 2025). "Analysis of clinical indicators based on Ann Arbor staging revealed that CHI3L1 levels were significantly higher in stage III-IV patients than in stage I-II patients (P = 0.001), suggesting that this biomarker is associated with tumor progression." (PMID 40260255, 2025). "CHI3L1 is a multifunctional protein highly expressed in inflammatory diseases and within the tumor microenvironment, contributing to a range of physiological and pathological processes." (PMID 40643503, 2025). "CHI3L1 is expressed in a wide range of cell types, including macrophages, neutrophils, tumor cells, inflammatory cells, vascular smooth muscle cells, and CNS-specific cells such as microglia, astrocytes, and neurons." (PMID 39827337, 2025). "In the previous study, we screened the high-affinity anti-CHI3L1 mAb in a human synthetic Fab phage display library, of which clone H1, which showed the highest ability to inhibit the metastasis and tumor growth in vivo, was selected." (PMID 41573517, 2025). "Immunohistochemical analysis revealed that CHI3L1 was expressed in both epidermal keratinocytes and tumor cells in CTCL lesions." (PMID 40260255, 2025). "Recent studies have suggested that CHI3L1 plays a crucial role in tumor immune escape by suppressing antitumor responses." (PMID 40900789, 2025). "For tumours with low or physiological levels of expression, anti-CHI3L1/Chil1 therapy has the potential to be deleterious." (PMID 40769579, 2025). "With the increasing application of immunotherapy in tumor treatment, the role of CHI3L1 in tumor immune escape has received considerable attention." (PMID 39068486, 2024). "In fact, CHI3L1 is elevated at both the mRNA and the protein levels in a variety of cancers and in many animal tumor models, and its levels were correlated with the stages and the outcomes of multiple types of primary and secondary carcinomas 12-16." (PMID 39513118, 2024). "CHI3L1(YKL40) also exhibits a pro-angiogenic effect, which can promote tumor angiogenesis through vascular endothelial cells and maintain vascular integrity through smooth muscle cells." (PMID 38543093, 2024). "As we all know, Chitinase 3-like protein -1 (CHI3L1), as a glycoprotein, assumes a pivotal role in governing various aspects of tumor cell behavior, including growth, proliferation, invasion, metastasis, angiogenesis, and activation." (PMID 38840908, 2024). "With regard to cancer angiogenesis, CHI3L1(YKL40) facilitates tumor vascularization through endothelial cells and maintains vascular integrity through smooth muscle cells." (PMID 38543093, 2024). "CHI3L1 was originally extracted and identified from osteosarcoma cell line culture medium, and afterwards, it was demonstrated that it can be released by tumor cells, immune cells, stromal-producing cells, etc.." (PMID 39000203, 2024). "Studies have shown that CHI3L1 is also derived from a variety of cells, including neutrophils, fibroblasts, vascular smooth muscle cells, chondrocytes, HSCs, and tumor cells." (PMID 38962736, 2024). "Dysregulation of CHI3L1(YKL40) promotes cell proliferation, invasion, migration, tumor angiogenesis, carcinogenesis, and chemoresistance." (PMID 38543093, 2024). "Chi3l1 co-opts neutrophils to mediate stromal restriction of T cells, whereas ablation of Chi3l1 ameliorates tumor growth and enhances the ICB response." (PMID 39107856, 2024). "CHI3L1 has the potential to enhance tumor growth and migration by interacting with TGF-β1 and TGFR, which subsequently activates the SMAD2/SMAD3 signaling pathway." (PMID 38177294, 2024). "High CHI3L1 RNA expression was found to be specific for GB compared to 30 other tumor types and related normal tissues." (PMID 38320988, 2024).
tumor (continued). "CHI3L1 is released into the TME, interacts with CD44 expressed on tumour‐associated macrophages, and activates the AKT pathway, thus promoting polarization of M2 macrophages." (PMID 38809929, 2024). "CHI3L1 activates immune cells (macrophages and neutrophils) and recruits them to the tumor site, where they release proinflammatory cytokines and chemokines, promoting inflammation and supporting cancer cell survival." (PMID 38177294, 2024). "They describe that knockdown of the CHI3L1 gene can significantly suppress tumor growth in mouse glioma models, highlighting its potential as a therapeutic target." (PMID 39768176, 2024). "Complementary immuno-assays on primary tumor tissue lysates identified local CHI3L1 and CHI3L3 production in both TNBC models, albeit higher in the 4T1 compared to the 66cl4 primary tumors." (PMID 38605414, 2024). "CHI3L1 can recruit immune cells, influence cell apoptosis, maintain cell proliferation signals, activate invasion, and initiate tumor development and metastasis under inflammatory conditions." (PMID 39068486, 2024). "The interaction between CHI3L1 and Gal-3 promotes the infiltration of monocyte-derived macrophages (MDMs) and induces their reprogramming into a tumor-promoting M2-like phenotype." (PMID 38275876, 2024). "CHI3L1 has been identified as a promoter of angiogenesis in neoplasms and has been shown to play a role in the activation of the mitogen-activated protein kinase/extracellular signal-regulated kinase pathway in endothelial cells." (PMID 39045955, 2024). "CHI3L1 can aggravate DNA oxidative damage, induce the cancerous phenotype, promote the development of a tumor inflammatory environment and angiogenesis, inhibit immune cells, and promote cancer cell growth, invasion, and migration." (PMID 39068486, 2024). "This is particularly important since CHI3L1 has been found overexpressed both in tumor cells and in cells from the TME, namely tumor-associated macrophages and cancer-associated fibroblasts." (PMID 38835347, 2024). "In inflammation-related lung cancer, CHI3L1 is a downstream product of the inflammation-associated transcription gene STAT3, which is substantially expressed before tumor formation." (PMID 39068486, 2024). "It is now well-established that CHI3L1 is endogenously expressed in a wide variety of cells, including neutrophils, macrophages, differentiated smooth muscle cell, endothelial cells, and tumor cells." (PMID 39513118, 2024). "Gal-3BP counteracts the tumor-promoting effect of CHI3L1 by binding to Gal-3 with a higher affinity." (PMID 39068486, 2024). "CHI3L1 is also known to be secreted by tumor and stromal cells, such as macrophages and fibroblasts." (PMID 38835347, 2024). "Immunohistochemistry identified significantly reduced Ly6G+ TAN and CD163+ M2 TAM stainings on primary tumor sections from anti-CHI3L1- compared to IgG control-treated mice, and add-on reductions of both markers in chitin-treated primary tumors." (PMID 38605414, 2024). "Previous studies have shown that CHI3L1 can stimulate the migration and invasion of cancer cells by modulating the tumor microenvironment." (PMID 38177294, 2024). "In a proof-of-concept study published in 2021, the local delivery of a peptide-based inhibitor targeting CHI3L1/Gal-3 (Gal3BP mimetic peptide) into brain tumors demonstrated the ability to induce tumor regression in treated mice." (PMID 38275876, 2024). "Recent research has revealed that both neutrophils and tumor cells can express and release CHI3L1 into the bloodstream, resulting in elevated serum levels in several cancer types." (PMID 40836974, 2024). "CHI3L1 has also been reported to have a proinflammatory function, which is thought to contribute to tumor growth and progression." (PMID 38177294, 2024). "It has been reported that CHI3L1 expression is highly upregulated with cancer-infiltrating macrophages, so-called TAM (tumor-associated macrophages)." (PMID 38667293, 2024).
tumor (continued). "Higher expression levels of CHI3L1(YKL40) have been associated with advanced stages of cancer, increased tumor size, and poor prognosis." (PMID 38543093, 2024). "Anti-CHI3L1 significantly reduced tumor growth compared to IgG control treatment, but chitin showed a significant add-on treatment effect compared to anti-CHI3L1." (PMID 38605414, 2024). "Further studies have shown that CHI3L1 can alter the oxidative stress in the tumor microenvironment, significantly diminishing the OS of patients." (PMID 39000203, 2024). "The role of Chitinase-3-like protein 1 (CHI3L1) in tumor progression has been gradually clarified in different kinds of solid tumors." (PMID 39000203, 2024). "Consistent with results from the in vitro model, ER stress-mediated apoptosis was greatly increased during tumor growth and in the lung metastatic tissue of CHI3L1-knockout (KO) mice." (PMID 37215572, 2023). "In comparison, the tumor growth rate and size in the BCSCs-231 + anti-CHI3L1 group were significantly lower than in the BCSCs-231 group." (PMID 37838657, 2023). "Consistent with immunoblotting results, the immunohistochemical analysis also showed increased CHOP and cleaved caspase 12 levels in tumor tissues from CHI3L1 KO mice." (PMID 37215572, 2023). "CHI3L1, a glycoprotein with a molecular weight of 40 kDa, is found to be up-regulated in non-neoplastic diseases characterized by chronic inflammation and tissue remodeling." (PMID 38173464, 2023). "The level of SOD1 protein was also significantly increased in lung tissues from metastatic and tumor sites of CHI3L1 KO mice, and the immune histochemical staining result confirmed this." (PMID 37215572, 2023). "Another report also showed that overexpression of CHI3L1 in PTC is closely related to tumor size, lymph node metastasis, and tumor invasion." (PMID 37480002, 2023). "The expression of Grp78 and phosphorylated PERK was also increased in tumor tissues from CHI3L1 KO mice." (PMID 37215572, 2023). "High levels of CHI3L1 are positively related to the infiltration of Tregs, neutrophils, and resting NK cells, which induces limitations in the effective anti-tumor immune response to GBM." (PMID 38019838, 2023). "A common CHI3L1 inhibitor, CHI3L1 neutralizing antibody, has been shown to significantly inhibit angiogenesis and tumor growth and promote tumor cell death in various diseases." (PMID 38003338, 2023). "CAF-derived Chi3L1 was observed to be another signaling axis between fibroblasts and immune cells, resulting in immunosuppressive and tumor-promoting microenvironment." (PMID 38313431, 2023). "To date, CHI3L1 is overexpressed in a variety of human and animal tumor models, and it is currently being considered a potential diagnostic marker and therapeutic target in oncology." (PMID 37091145, 2023). "The present study provides important insights into the role of CHI3L1 in the regulation of ER stress associated UPR function and apoptosis, as well as the SOD1 dependent regulation of tumor growth." (PMID 37215572, 2023). "Immunohistochemistry analysis showed increased expression of Grp78 and phosphorylated PERK in tumor tissues of CHI3L1 KO mice." (PMID 37215572, 2023). "Recent findings indicate that CHI3L1/YKL40 is highly expressed only in a small fraction of the primary tumor samples." (PMID 36900355, 2023). "An orthotopic B.C. transplanted tumor model in mice with humanized immune systems was constructed, in which the Role of CHI3L1/MAF/CTLA4 in the immune escape of TNBC was explored." (PMID 37838657, 2023). "Taken all together, CHI3L1 depletion is expected to reduce the ability of autophagy to promote tumor metastasis." (PMID 37340009, 2023). "For instance, in GBM stem‐like cells (GSCs) with methylated O6‐methylguanine‐DNA methyltransferase promoter (MGMT‐m), CHI3L1 functioned as a tumour suppressor gene, sensitizing GSCs' response to temozolomide (TMZ) by activating DNA damage responses (DDRs)." (PMID 37902124, 2023).
tumor (continued). "It has also been reported that CHI3L1 promotes glioma progression via the NF-κB signaling pathway and reprograms the tumor microenvironment." (PMID 37759870, 2023). "CHI3L1 is secreted and expressed by various cells, including macrophages, neutrophils, tumor cells, and vascular smooth muscle cells." (PMID 38003338, 2023). "In vivo, CAFs promote tumor growth and recruitment by expressing CHI3L1 and activating macrophage MAPK and PI3K signaling pathways to downregulate M1 macrophage-associated factors and promote M2 polarization." (PMID 38003338, 2023). "Consistent with the in vitro model, the expression of autophagy-related proteins was downregulated in the tumor tissues of CHI3L1-knockout mice." (PMID 37340009, 2023). "The overexpression of CHI3L1 alters the tumor microenvironment, thereby enhancing the metastatic potential and sensitivity to cetuximab in CRC." (PMID 38003338, 2023). "In GBM, CHI3L1 regulates tumorigenesis by interrupting the pathways leading to apoptosis and by remodeling the extra-cellular matrix to create a good substrate for tumor growth." (PMID 37511403, 2023). "In mouse models of A549 lung cancer, the administration of anti-CHI3L1 antibodies has been observed to modulate the tumor microenvironment." (PMID 38003338, 2023). "Patients with overexpressed CHI3L1 tumor cells have a high rate of tumor metastasis and a low survival rate." (PMID 37887529, 2023). "Although it is known that CHI3L1 can create a tumor-promoting environment by regulating T cells and macrophages, its association with neutrophils has only been explored in liver inflammation and cystic fibrosis." (PMID 37958973, 2023). "Western blot also confirmed that CHI3L1 was significantly up-regulated in tumor sites than in peritumor cores, and its expression increased along with the increase of WHO grade of giloma." (PMID 36276655, 2022). "The expression of MMP9 and cyclin D1 was also suppressed in anti‐Chi3L1 antibody‐treated lung metastasis tumor tissues." (PMID 34861103, 2022). "Among them, cluster 10 was defined as CHI3L1high tumor cells with high expression of CHI3L1, while others were attributed to the CHI3L1low group." (PMID 36276655, 2022). "We analyzed TCGA pan-cancer and GTEx (15776 samples in total) mRNA data to compare the expression levels of CHI3L1 in 33 tumor types and paired normal tissues." (PMID 36276655, 2022). "Our ELISA data in animal models indicated a positive correlation of plasma CHI3L1 level and tumor size." (PMID 34987649, 2022). "Synergistic cytotoxic T cell-induced tumor cell death and the heightened induction of the tumor suppressor PTEN were seen in co-cultures of T and tumor cells treated with bispecific antibodies that target both CHI3L1 and CTLA-4." (PMID 36618349, 2022). "Murine modeling showed that CHI3L1 administration resulted in increased tumor growth and a change in the immune cell repertoire, including increased macrophages and decreased NK and T cell infiltration." (PMID 36291900, 2022). "Further, CHI3L1 were released into the tumor microenvironment (TME) and interacted with CD44 expressed on tumor-associated macrophages to activate AKT pathway, thereby contributing to M2 macrophage polarization." (PMID 36276655, 2022). "The mRNA levels of CHI3L1/YKL-40 were significantly upregulated in GBM tumor tissue compared to normal tissue." (PMID 36408158, 2022). "The results demonstrated that high Rab37 expression showed concordantly increased CHI3L1 level in the tumor infiltrated CD4+ T cells, CD8+ T cells and F4/80+ macrophages." (PMID 34987649, 2022). "Secreted by a multitude of cells including macrophages, neutrophils, as well as tumor cells, CHI3L1 plays a vital role in tissue injury, inflammation, tissue repair, and remodeling response." (PMID 35646113, 2022). "Immune blot results showed that MMP2, MMP9, and MMP13 (migration marker proteins) expression decreased in tumor tissues of anti‐Chi3L1 antibody‐treated mice." (PMID 34861103, 2022).
tumor (continued). "Chi3L1 immunohistochemistry decreased significantly in the tumor tissue of mice treated with anti‐Chi3L1 antibody." (PMID 34861103, 2022). "It has been demonstrated that chitinase 3-like 1 (Chi3l1) dysregulation, present in many solid tumors, inhibits the accumulation of phosphorylated cofilin, hence promoting tumor cell metastasis, however, activation of RIG-like helicase can rescue this process." (PMID 35371070, 2022). "In summary, our study revealed that nuclear CHI3L1 contributed to tumor cell proliferation and survival via sustained activation of the NF-κB signaling pathway." (PMID 36276655, 2022). "Multiplex fluorescence immunohistochemistry was performed to detect the protein level of Rab37 and CHI3L1, and localization of the tumor-infiltrating immune cells in allografts from mice or tumor specimens from cancer patients." (PMID 34987649, 2022). "Considering its ubiquity in the various pathologies, and its abundance in cultured medium, the roles of CHI3L1 in cellular senescence, especially in cancerous epithelial cells and tumor microenvironment, is worthy of future investigation." (PMID 34667277, 2022). "Several of the most highly induced genes, CHI3L1, GPX1, PLIN1, PLIN4, and JAK3, have been linked to enhanced growth or cell survival in other tumor types." (PMID 35787784, 2022). "In fact, genetic in vivo ablation of Chi3L1 in fibroblasts reduced tumor growth and macrophage recruitment while enhancing tumor infiltration by T cells." (PMID 35814444, 2022). "Considering the multiple roles of CHI3L1 in tumorigenesis and low basal level in normal epithelial cells, the direct neutralization of secreted intratumoral CHI3L1 will inhibit tumor progression." (PMID 34987649, 2022). "This study provides new mechanistic insights into the antitumor function of anti‐Chi3L1 antibody in a tumor microenvironment, which can regulate tumor metastasis and affect macrophage biology." (PMID 34861103, 2022). "We investigated the anti‐Chi3L1 antibody‐mediated effect on the altered expression of macrophage polarization proteins in lung metastatic tumor tissues." (PMID 34861103, 2022). "The volume of vehicle‐treated tumor tissues (1.57 ± 0.59) was dramatically decreased to 0.58 ± 0.31 in anti‐Chi3L1 antibody‐treated mice, and the volume of tumor tissue was lower compared with Avastin." (PMID 34861103, 2022). "Our previous study demonstrated that the protein expression of CHI3L1 is elevated by the tumor stage‐dependent pattern in human lung tumor tissues." (PMID 34758182, 2022). "These IF-IHC results demonstrated novel findings that nCHI3L1 Ab therapies reduce CHI3L1 accumulation and shaped an anti-tumor immunity TME to suppress tumor growth and metastasis." (PMID 34987649, 2022). "Creation of an immunosuppressive tumor microenvironment (TME) has been suggested as a possible mechanism of CHI3L1-induced cancer promotion." (PMID 34987649, 2022). "We have previously developed a humanized monoclonal antibody targeting Chi3L1 which significantly inhibited tumor growth and metastasis in vivo." (PMID 34861103, 2022). "CHI3L1, namely chitinase 3-like 1 protein, was a secretory glycoprotein which promoted tumor infiltration and migration in various neoplasms by elevating the expression levels of matrix metalloproteinase (MMPs) family genes." (PMID 36299288, 2022). "The expression level of cell cycle‐related proteins, such as cyclin D1, cyclin E, Cdk2, Cdk4, Cdk6, and PCNA was also decreased in anti‐Chi3L1 antibody‐treated lung metastasis tumor tissue." (PMID 34861103, 2022). "Chitinase 3-like-1 (CHI3L1) is induced in many cancers where it portends a poor prognosis and contributes to tumor metastasis." (PMID 36618349, 2022). "Specific ligand–receptor interactions between CHI3L1+ mTEC-like tumor cells and CD8+ TRM cells were identified." (PMID 36115836, 2022). "Compared with the vehicle, the expression of CD68 and F4/80 was significantly reduced in anti‐Chi3L1 antibody‐treated tumor tissues." (PMID 34861103, 2022).